KIF20B (kinesin family member 20B)
Description:
Plus-end-directed motor enzyme that is required for completion of cytokinesis. Required for proper midbody organization and abscission in polarized cortical stem cells. Plays a role in the regulation of neuronal polarization by mediating the transport of specific cargos. Participates in the mobilization of SHTN1 and in the accumulation of PIP3 in the growth cone of primary hippocampal neurons in a tubulin and actin-dependent manner. In the developing telencephalon, cooperates with SHTN1 to promote both the transition from the multipolar to the bipolar stage and the radial migration of cortical neurons from the ventricular zone toward the superficial layer of the neocortex. Involved in cerebral cortex growth (By similarity). Acts as an oncogene for promoting bladder cancer cells proliferation, apoptosis inhibition and carcinogenic progression.
Synonyms: CT90; MPP1; KRMP1; MPHOSPH1; MPP-1
Tractability: PROTAC: ubiquitination databases record sites on it; a small molecule that binds it is known.
Target class: Other cytosolic protein
Gene: Protein-coding gene on chromosome 10 (89,701,583 to 89,774,939, forward strand). Ensembl gene ENSG00000138182.
Subcellular location: Nucleus; Cytoplasm, cytoskeleton, microtubule organizing center, centrosome; Nucleus, nucleolus; Nucleus, nucleoplasm; Cytoplasm, cytoskeleton, spindle; Cytoplasm, cytoskeleton, spindle pole; Midbody; Cell projection, axon; Cell projection, growth cone
Subcellular location (Human Protein Atlas): Basal body; Cytokinetic bridge; Nucleoplasm; Centrosome; Cytosol; Midbody; Perinuclear theca
Pathways (Reactome):
Hemostasis: Kinesins
Vesicle-mediated transport: COPI-dependent Golgi-to-ER retrograde traffic
Gene Ontology:
Molecular function: ATP hydrolysis activity; microtubule binding; plus-end-directed microtubule motor activity; protein binding; protein homodimerization activity; WW domain binding; ATP binding; microtubule motor activity
Biological process: positive regulation of cell population proliferation; positive regulation of cytokinesis; neuron projection morphogenesis; positive regulation of intracellular protein transport; positive regulation of mitotic cytokinetic process; positive regulation of neuron migration; protein localization to microtubule; regulation of cell cycle; regulation of establishment of cell polarity; regulation of mitotic nuclear division; microtubule-based movement
Cellular component: centrosome; ciliary basal body; contractile ring; cytoplasm; midbody; mitotic spindle midzone; mitotic spindle pole; nucleolus; nucleoplasm; nucleus; kinesin complex; perinuclear region of cytoplasm; spindle midzone; axon; growth cone; microtubule cytoskeleton; spindle; spindle pole
Genetic constraint (gnomAD): Loss-of-function variants: 90 observed, 120.85 expected, observed/expected ratio (o/e) 0.74, 90% interval 0.63 to 0.89. The upper end of that interval is the gene's LOEUF score, 0.89, which puts it in group 3 of 6, group 1 being the genes least tolerant of losing a copy. Missense variants: 1,362 observed, 1,290.1 expected, observed/expected ratio (o/e) 1.06, 90% interval 1.01 to 1.1. Synonymous variants: 462 observed, 443.83 expected, observed/expected ratio (o/e) 1.04, 90% interval 0.96 to 1.12.
Homologues: Orthologues: chimpanzee KIF20B (99% identical), macaque KIF20B (96% identical), dog KIF20B (82% identical), pig KIF20B (80% identical), rabbit KIF20B (78% identical), guinea pig KIF20B (75% identical), mouse Kif20b (72% identical), rat Kif20b (72% identical), tropical clawed frog kif20b (45% identical), zebrafish kif20ba (33% identical), zebrafish kif20bb (29% identical).
Diseases named in the same sentence as KIF20B in open-access papers:
KIF20B is named in the same sentence as 36 diseases in open-access papers, as found by Europe PMC text mining. Sharing a sentence is not in itself a finding about the gene and the disease. The quoted sentences say what the papers report.
bladder cancer (9 papers, 2016 to 2024). "KIF20B is overexpressed in bladder cancer and is considered as a cancer-testis antigen specific to human bladder cancer." (PMID 35812733, 2022). "We subsequently found KIF20B gene, which was previously reported as an oncogenic CT antigen in bladder cancer." (PMID 34065612, 2021).
pancreatic cancer (7 papers, 2021 to 2025). "Within these two cell cycle genes, KIF20B can promote cell proliferation and could be a potential therapeutic target in pancreatic cancer." (PMID 36061171, 2022). "Consequently, the gene set enrichment analysis (GSEA) showed that KIF20B and KIF21B’s overexpression was associated with the immunological and oncogenic pathway activation in pancreatic cancer." (PMID 34557409, 2021). "For prognostic prediction, we developed an immune-related prognostic risk model (IRPM) based on four immune-related prognostic genes in pancreatic cancer, RHOF, CEP250, TSC1, and KIF20B." (PMID 38203311, 2023). "The mRNA expression levels of CSTF2, FAF2, KIF20B, AKR1A1, APOM, KRT6C, and CD70, which were included in the prognostic model, were detected in different types of pancreatic cancer cell lines." (PMID 38268915, 2023). "Ultimately, KIF20B and KIF21B were used to build a two-gene panel for predicting the survival of pancreatic cancer patients." (PMID 34557409, 2021). "Next, we investigated the gene expression of KIF20B and KIF21B in pancreatic cancer cell lines and normal pancreatic cell." (PMID 34557409, 2021). "In conclusion, KIF20B and KIF21B were highly expression in most pancreatic cancer cell lines compared to normal pancreatic cell." (PMID 34557409, 2021). "Finally, real-time quantitative PCR (RT-qPCR) was utilized to investigate the expression pattern of KIF20B and KIF21B in pancreatic cancer cell lines and normal pancreatic cell." (PMID 34557409, 2021).
hepatocellular carcinoma (5 papers, 2020 to 2024). A malignant tumor that arises from hepatocytes. "A recent study suggested to target the KIF20B gene in the treatment for hepatocellular carcinoma." (PMID 32923390, 2020).
clear cell renal cell carcinoma (2 papers, 2022 to 2024). "It has been reported that KIF20B promoted the progression of clear cell renal cell carcinoma, and KIF18B promotes cell proliferation in colon adenocarcinoma." (PMID 38713252, 2024).
colorectal cancer (2 papers, 2023 to 2024). A primary or metastatic malignant neoplasm that affects the colon or rectum. "Moreover, KIF20B mediates colorectal cancer cell migration and invasion though promoting EMT process." (PMID 35796646, 2023).
microcephaly (2 papers, 2017 to 2020). A congenital or acquired developmental disorder in which the circumference of the head is smaller than normal for the person's age and sex. "We previously isolated a loss-of-function mouse mutant of Kif20b and showed that it had a thalamocortical axon guidance defect and microcephaly." (PMID 28359322, 2017). "Furthermore, in addition to Citron kinase and RhoA, three members of Kinesin family, Kif20a, Kif20b, and Kif4 regulate neocortical NPC cytokinesis and mutations of these genes result in reduced cortical size with microcephaly." (PMID 32159512, 2020). "Since the Kif20b mouse mutant is a novel model for human microcephaly, it is important to know that there could be defects in connectivity in addition to the small brain size in some cases of microcephaly." (PMID 28359322, 2017).
tongue cancer (2 papers, 2022). A malignant neoplasm affecting the tongue. "Additionally, KIF20B could promote cancer growth by promoting cell proliferation in tongue cancer." (PMID 35359374, 2022).
colon cancer (1 paper, 2019). "In keeping with these important roles, multiple studies have shown that knockdown of KIF20B in bladder, liver and HCT116 colon cancer cells results in cytokinetic defects that are reflected in accumulation of multinucleated cells that eventually undergo apoptosis." (PMID 30804394, 2019).
intervertebral disc degeneration (1 paper, 2025).
liver cancer (1 paper, 2021). An epithelial or non-epithelial malignant neoplasm that arises from the liver. "A more recent report showed that blocking cytokinesis by KIF20B inhibition increased the efficacy of microtubule-associated therapeutic agents in liver cancer." (PMID 34832109, 2021). "Upregulated tissue expression of Kinesin-like protein KIF20B has been reported in some solid tumours including breast, bladder and liver cancers and is consistent with reduced packaging into circulating Evs." (PMID 34832109, 2021).
meningioma (1 paper, 2020). A generally slow growing tumor attached to the dura mater. "The role of KIF20B in tumorigenesis of meningiomas, especially multiple lesions, suggests that its suppression might be a novel strategy in the treatment for multiple meningiomas in the future." (PMID 32923390, 2020).
myeloid malignancies (1 paper, 2017). "Most of the significantly mutated genes were previously well documented either in MDS or other myeloid malignancies, although some were newly identified or re-confirmed as recurrently mutated genes in our analysis, such as ROBO1/2, IHIT3, KIF20B, PTPRD, ANKRD11 and DHX9." (PMID 28220884, 2017).
neuropathies (1 paper, 2019). "Human autoantibodies directed against KIF20B have been described in up to 25% of patients with idiopathic ataxia and less commonly in other neuropathies and autoinflammatory conditions." (PMID 31260385, 2019).
cancer (15 papers, 2013 to 2024). A tumor composed of atypical neoplastic, often pleomorphic cells that invade other tissues. "Clinical trial of peptides cancer vaccine therapy, which was derived from KIF20B, showed sufficient tolerance and effective induction of peptide-specific cytotoxic T lymphocytes." (PMID 34065612, 2021). "Our findings suggest that USP7 and FBXO38 may both be useful targets for inhibiting the growth of cancer cells with KIF20B overexpression." (PMID 30804394, 2019). "Consequently, KIF20B is recognized as a potential therapeutic target for these cancers, since depletion of KIF20B in these cells leads to mitotic arrest, through failure of cytokinesis, and subsequent apoptosis." (PMID 30804394, 2019). "Similarly, the overexpression of USP7 that has been reported in many cancer cells may also induce their proliferation by upregulating KIF20B and promoting cytokinesis." (PMID 30804394, 2019). "Finally, KIF20B is elevated in several cancers, and while that could be due to its role in cell division, our data suggest it could also be due to effects on cell motility and morphology that could enhance metastasis." (PMID 28359322, 2017).
tumor (8 papers, 2013 to 2024). "KIF20B was not only related to tumor sizes and T stage but also promoted the progression of ccRCC by stimulating cell proliferation." (PMID 34557409, 2021). "The ‘tumor cells 1’ cluster had the gene expression characteristic of stem-like tumor cells with an elevated expression of genes involved in cell division and chromosome segregation such as Top2a, Mki67, Cenpf, Cenpe, Incenp, Anln, Ccna2, Kif20b, Ccnb1, and Smc4." (PMID 39769061, 2024). "After tumor mutation profile and copy number variation (CNV) analyses, we established and validated a prediction model of KRAS mutations, based on survival analysis and mRNA expression, that contained seven genes: CSTF2, FAF2, KIF20B, AKR1A1, APOM, KRT6C, and CD70." (PMID 38268915, 2023). "In this study, 105 immune-related genes from tumor gene sets were identified as IRPGs in PAAD patients by the univariate Cox analysis, and 4 genes of IRPGs, RHOF, CEP250, TSC1, and KIF20B were then used to construct the IRPM." (PMID 38203311, 2023).
KIF20B also shares sentences with these, for which no sentence is quoted: breast carcinoma (3 papers); ovarian carcinoma (2); airway allergy (1); Allergy (1); Ataxia (1); autoimmune disease (1); colon adenocarcinoma (1); demyelinating polyneuropathy (1); disc degeneration (1); esophageal cancer (1); Fanconi anemia (1); metastatic prostate carcinoma (1); neurodegenerative disease (1); oral cancer (1); paroxysmal nocturnal hemoglobinuria (1); psoriasis (1); renal carcinoma (1); renal cell carcinoma (1); rheumatoid arthritis (1); thyroid cancer (1); urothelial carcinoma of the bladder (1).